FGF2 (fibroblast growth factor 2)
Diseases named in the same sentence as FGF2 in open-access papers (continued):
Sharing a sentence is not in itself a finding about the gene and the disease.
ischemic stroke (32 papers, 2013 to 2025). A stroke disorder caused by obstruction of blood flow to the brain, due to thrombotic (local blood clot formation) or embolic (due to a blood clot or other material traveling from another site) event. "Furthermore, we detected the expressions of AQP4 and Cx43, astrocytic A1/A2 reactivity, and FGF2/PI3K/AKT pathway to develop in-depth knowledge of the possible repair mechanisms underlying TMP treatment after ischemic stroke." (PMID 37051111, 2023). "Ischemic stroke promotes neurogenesis by several growth factors including FGF-2, IGF-1, BDNF, VEGF, and chemokines including SDF-1 and MCP-1." (PMID 35035503, 2022). "In recent years, studies suggested ischemic stroke via several growth factors promotes neurogenesis, including FGF-2, IGF-1, BDNF, VEGF, and chemokines, including SDF-1, MCP-1." (PMID 35625017, 2022). "Overall, our study suggests that Sal is an effective treatment for ischemic stroke that functions via the FGF2-mediated cAMP/PKA/CREB pathway to promote dendritic and synaptic plasticity." (PMID 32518214, 2020). "For example, emerging data suggests downregulation of miR-15a in cerebral vessels in a murine model of ischemic stroke promotes angiogenesis in the peri-infarct region by increasing FGF-2 and VEGF levels." (PMID 29285679, 2018). "Shifting A1 to A2 reactivity, suppressing excessive AQP4 and Cx43 expression of astrocytes, and activating FGF2/PI3K/AKT pathway might be potential mechanisms of promoting neurovascular restoration with TMP after ischemic stroke." (PMID 37051111, 2023). "The FGF2-mediated aberrantly activated cAMP/PKA/CREB pathway is a critical immunological signaling cascade associated with dendritic and synaptic plasticity and thus contributes to recovery after ischemic stroke." (PMID 32518214, 2020). "The FGF2/PI3K/AKT pathway may be involved in neurovascular repair in ischemic stroke." (PMID 39497721, 2024). "Following brain damage, such as traumatic brain injury or ischemic stroke, NPCs in the dentate gyrus are activated by injury-induced signals, including growth factors like brain-derived neurotrophic factor (BDNF) and fibroblast growth factor-2 (FGF-2), as well as inflammatory cytokines." (PMID 41291782, 2025). "In addition, Sal acts as an effective treatment option through the FGF2-mediated cAMP/PKA/CREB signaling pathway to reduce inflammation, apoptosis and promote dendritic and synaptic plasticity after ischemic stroke." (PMID 32518214, 2020).
pulmonary fibrosis (32 papers, 2006 to 2025). Chronic progressive interstitial lung disorder characterized by the replacement of the lung tissue by connective tissue, leading to progressive dyspnea, respiratory failure, or right heart failure. "The findings would provide a basis for clinical application of FGF2 in treatment of lung repair and inhibition of pulmonary fibrosis." (PMID 37583315, 2023). "It was also found that FGF2 mediated pulmonary fibroblast differentiation and pulmonary fibrosis, potentially though its inhibition of TGF-β-induced phosphorylation of p38 MAPK and c-Jun N-terminal kinase (JNK)." (PMID 36102060, 2022). "Another related study demonstrated that FGF2 decreased bleomycin-induced pulmonary fibrosis by inhibition fibroblast activation and collagen production suggesting FGF2 is an antifibrotic factor." (PMID 36102060, 2022). "Overexpression of FGF2 has similarly been reported to inhibit myofibroblast differentiation in vitro and pulmonary fibrosis in vivo." (PMID 33561015, 2021). "Another study showed that FGF2 also decreases bleomycin-induced lung fibrosis in mice with inducible FGF2 expression." (PMID 34831463, 2021). "As to bleomycin-induced lung injury and pulmonary fibrosis, more Fgf2 knockout mice succumb to death due to compromised epithelial repair process and barrier function recovery." (PMID 32300593, 2020). "For example, neotuberostemonine, a natural alkaloid isolated from Stemona tuberosa, was applied to decrease the levels of FGF2 in bleomycin-induced pulmonary fibrosis mice." (PMID 32300593, 2020). "Overall, angiogenic proteins implicated in tissue injury and fibrosis (TGF-β1, FGF-2, EGF, and HB-EGF) were maintained at euthermic levels during torpor, so it is unlikely that there is any lasting lung fibrosis or injury in hibernating animals." (PMID 31763078, 2019). "FGF2 was notrequired for the generation of bleomycin-induced lung fibrosis, whereas it was essentialfor lung epithelial recovery." (PMID 28916723, 2017). "FGF-2 is released after tissue injury and during inflammation, and is crucial in the development of lung fibrosis." (PMID 19014534, 2008). "Furthermore, other research has shown that FGF2 protein levels significantly increase in mice with pulmonary fibrosis induced by bleomycin." (PMID 38625722, 2024). "Further studies are required to precisely understand how FGF‐2 regulates lung fibrosis." (PMID 37583315, 2023). "Taken together, these findings indicate that FGF2 acts as an upstream regulator of the inhibition of PFs activation and may play a regulatory role in pulmonary fibrosis." (PMID 37583315, 2023). "FGF2 has been reported to be profibrotic, but it was also recently demonstrated that its overexpression may instead protect from bleomycine-induced pulmonary fibrosis, through promotion of proliferation and myofibroblast dedifferentiation." (PMID 34572381, 2021). "It is, however, likely that, in vivo, an imbalance in concentrations of cytokines, present in the microenvironment, particularly TGFβ and FGF2, may influence the course of pulmonary fibrosis, as well as the response to therapy." (PMID 34572381, 2021). "Interestingly, further studies using mice with an inducible FGF2 expression demonstrated that FGF2 also suppressed the bleomycin-induced lung fibrosis." (PMID 34360000, 2021). "Therefore, msFGFR2c could inhibit the promoting effects of TGF-β, CTGF, and FGF-2 during lung fibrosis and has the potent clinical value for the treatment of pulmonary fibrosis." (PMID 32130565, 2020). "Building on these findings, our study explored the therapeutic potential of P5, a small peptide derived from fibroblast growth factor 2 (FGF2), in treating pulmonary fibrosis." (PMID 39859240, 2025). "The present study testing RC28-E, previously identified as a block of VEGF-A, PlGF, FGF-2, and PDGF, demonstrated that RC28-E attenuates established lung fibrosis by blocking VEGF and FGF-2 in an in vivo bleomycin-induced model." (PMID 31652997, 2019).
pulmonary fibrosis (continued). "This study highlighted that blocking the wingless-related integration site (Wnt)/β-catenin signaling pathway may reduce FGF2 expression in both AT2 cell lines stimulated by bleomycin in vitro and in a mouse model of bleomycin-induced pulmonary fibrosis." (PMID 38625722, 2024). "Furthermore, ELISA was used to detect pulmonary fibrosis markers COL-1, COL-3, WNT, Vimentin, β-Catenin, Fibronectin, α-SMA, N-Cadherin, E-Cadherin, TWIST, CTGF, FGF2, PDGF-α, MMP2, MMP8, MMP9, MMP13, TIMP1, TGF-β, Smad2, and Smad3 expression levels." (PMID 37812357, 2023). "FGF2 and its receptor (FGFR) are highly expressed in the lung fibrosis tissues." (PMID 37583315, 2023). "Guzy and Xiao found that FGF2 is required for epithelial recovery following bleomycin‐induced lung injury in mice, but not for pulmonary fibrosis." (PMID 37583315, 2023). "It has been confirmed that suppression of the Wnt/β‐catenin signaling could significantly alleviate bleomycin‐induced pulmonary fibrosis accompanied by reducing expression of TGF‐β1 and FGF2 in vitro and in vivo." (PMID 37583315, 2023). "Fibroblast growth factor 2 (FGF2) can inhibit fibrotic gene expression and suppress the differentiation of pulmonary fibroblasts (PFs) into myofibroblasts in vitro, suggesting that FGF2 is a potential target for inhibiting pulmonary fibrosis." (PMID 37583315, 2023). "In this study, we suggest that RC28-E might alleviate lung fibrosis by neutralizing or blocking VEGF and FGF-2, thus attenuating their effects on fibroblast activation." (PMID 31652997, 2019). "FGF2 has been shown to be required for epithelial recovery, but not for pulmonary fibrosis, in response to bleomycin, which calls for more studies to explore the role of FGF2 as a profibrotic growth factor in vivo." (PMID 28974056, 2017). "However, our research did not establish the specific pathway through which Fgf2 promotes pulmonary fibrosis." (PMID 38625722, 2024).
liver fibrosis (31 papers, 2010 to 2025). "Other studies have shown that FGF2‐deficient mice exhibit reduced liver fibrosis after CCl4 administration, suggesting that FGF2 is a potential candidate profibrogenic factor." (PMID 32901093, 2020). "In another study, liver fibrosis resulting from chronic exposure to CCl4 was markedly decreased in the liver of FGF1/FGF2-deficient mice." (PMID 31652997, 2019). "In another study, liver fibrosis resulting from chronic exposure to CCl4 was markedly decreased in liver of FGF1/FGF2-deficient mice." (PMID 31652997, 2019). "Liver fibrosis resulting from chronic carbon tetrachloride (CCl4) exposure has been shown to be markedly decreased in FGF1/FGF2-deficient mice." (PMID 24710173, 2014). "In another study, liver fibrosis resulting from chronic CCl4 exposure was markedly decreased in the livers of FGF1/FGF2-deficient mice." (PMID 24710173, 2014). "However, excessive FGF2 signaling has been linked to hepatic fibrosis, suggesting that its upregulation in aged HFD-fed mice likely contribute to liver damage rather than protection." (PMID 40585885, 2025). "Autocrine FGF2 and the high expression of FGFR1 in HSCs and the activation of the FGF2/FGFR1 signaling pathway in HSCs have been demonstrated to play an important role in the regulation of liver fibrosis, cirrhosis, and tumor progression." (PMID 35951441, 2022). "The effect of Heparanase inhibition on liver fibrosis was assessed by using Picrosirius red and Masson Trichrome stainings and measuring the pro-fibrotic cytokines FGF-2 and protein kinase B (AkT) in liver homogenates." (PMID 35329997, 2022). "Neratinib inhibited FGF2 expression in activated HSCs and serum FGF2 level in the model, suggesting that neratinib possessed therapeutic potency against liver fibrosis and the potential for application against other fibrotic diseases." (PMID 32901093, 2020). "ADSCs can also have their therapeutic potential in liver fibrosis enhanced by preconditioning with cytokines, polyphenols, 3D culture, transfection with plasmids (FGF-2), HGF, and miRNA." (PMID 31671842, 2019). "In vivo, liver fibrosis was also improved with FGF2-transfected ADSCs transplantation in thioacetamide-induced hepatic fibrosis." (PMID 31671842, 2019). "We have also revealed that pharmacological application of FGF2 attenuates theprogression of liver fibrosis in an experimental murine BDL model, indicating that FGF2is a candidate anti-fibrotic agent for the treatment of liver fibrosis." (PMID 28916723, 2017). "In conclusion, FGF2 triggersCYGB gene expression and deactivation of myofibroblastic humanHSCs, indicating that FGF2 has therapeutic potential for managing liver fibrosis." (PMID 28916723, 2017). "Of note, in bileduct–ligated mice, FGF2 administration ameliorated liver fibrosis andsignificantly reduced HSC activation." (PMID 28916723, 2017). "We also show that FGF2 administration ameliorates liver fibrosis induced bybile duct ligation (BDL) in mice." (PMID 28916723, 2017). "A previous study reported improvement in liver fibrosis with combined treatment of FGF2 and MSCs by regulating the expression of metalloproteinases (MMPs) and ultimately reduction in matrix proteins." (PMID 22533821, 2012). "Notably, differential effects between the LMW and HMW isoforms of FGF2 have been documented in the context of liver fibrosis and osteoarthritis development." (PMID 39436561, 2024). "FGF2 is a known contributor to liver fibrosis, and an anti-fibrotic effect has recently been hypothesized." (PMID 34062967, 2021). "Overall, the differential expression of 5,449 genes were detected and three genes which regulate the expression of connective tissue growth factor, fibroblast growth factor 2 and netrin 4, each associated with HSC activation and liver fibrosis, were identified." (PMID 34648138, 2021). "Also, this study suggests that neratinib targets the inhibition of FGF2 as a novel candidate to alleviate aHSC, a potential target for liver fibrosis." (PMID 32901093, 2020).
liver fibrosis (continued). "The mice that lack FGF1 and FGF2, liver fibrosis was decreased." (PMID 31031647, 2019). "Furthermore, several lncRNAs target genes that have been reported to associated with HSC activated and liver fibrosis, such as CTGF, FGF2, FGFR1, IGFBP7 and NTN4." (PMID 29495545, 2018). "Moreover, in a bile-duct-ligated mouse study, FGF2 administration also ameliorated hepatic fibrosis and significantly reduced HSC activation." (PMID 29495545, 2018). "Furthermore, the inhibition of fibroblast growth factor receptor (FGFR) 1, the predominant receptor for FGF2, ameliorated hepatic fibrosis in a rodent model." (PMID 26243655, 2015). "Indeed, the double knockout of FGF1 and FGF2 significantly decreases chemically induced liver fibrosis, while transgenic expression of FGF2 in cardiomyocytes exacerbated myocardial injury." (PMID 22606265, 2012). "Here, we demonstrate that in the MDR2-KO mouse model of chronic liver inflammation that culminates into hepatocarcinogenesis that FGF21 is expressed in hepatocytes and FGF2 is specifically expressed in stellate cells which may indicate its role in liver fibrosis in chronic liver inflammation." (PMID 37770545, 2023). "A variety of factors, including PDGF, FGF-2, VEGF, β-catenin, Axin 2, TGF-β1, PAI-1, collagen I, and α-SMA, are key mediators of hepatic fibrosis." (PMID 33178320, 2020). "For instance, FGF2 activates FGFR1 signaling in HSCs and upregulates the level of the CyGB gene to inhibit the transformation of HSCs into myofibroblasts and thereby alleviates liver fibrosis and cirrhosis." (PMID 35951441, 2022). "However, it remains unknown whether the lncRNA mediate FGF2, FGFR2 or participated in the Hippo pathway to regulate liver fibrosis." (PMID 29495545, 2018). "Furthermore, one of the observation is that the expression levels of FGF2 and NTN4 increased in VPA (quiescent hHSC) and consistent with the previous report, which suggested that their targeted lncRNAs likely have these function in hepatic fibrosis." (PMID 29495545, 2018).
ulcer (31 papers, 2009 to 2025). "In a univariate analysis using logistic regression, an increase in plasma FGF-2 was tied to greater odds of high-grade ulcers (OR 1.16; 95% CI 1.02–1.38, p = 0.043)." (PMID 37371653, 2023). "In the univariate analysis using logistic regression, an increase in plasma FGF-2 was tied to greater odds of high-grade ulcers according to the SINBAD classification (OR 1.16; 95% CI 1.02–1.38, p = 0.043)." (PMID 37371653, 2023). "In contrast, greater variability in mean plasma FGF-2 levels and ulcer healing by 12 months is observed." (PMID 37685648, 2023). "Mean plasma FGF-2 values were higher among patients who achieved ulcer healing only up to the first month, which can suggest confounding of this relationship by other factors given a longer period of observation." (PMID 37685648, 2023). "The topical application of propolis gel upregulated the expression of FGF-2 and fibroblasts in promoting ulcer healing in streptozotocin-induced diabetic rats." (PMID 36500579, 2022). "The FGF-2 preparation used in this experiment is already covered by insurance in Japan for ulcer treatment, and PELNAC is also covered by insurance as bilayer artificial dermis." (PMID 30022246, 2019). "FGF-2 used in this study is already approved in Japan for ulcer treatment, and the safety of its local administration has been established." (PMID 30022246, 2019). "Ulcers treated with 0.01% rh-FGF2 showed a 75% or greater reduction in the area of the ulcer compared with the placebo group." (PMID 29949887, 2018). "Mixed cell implantation in this ulcer model reduced TNF-α and IL-6 levels in the tissues surrounding the mixed cell sheet-treated ulcers compared with controls or mice treated with trafermin (FGF2)." (PMID 28687753, 2017). "The results showed that, compared with placebo-treated patients, the number of FGF2-treated patients whose ulcers shrank by 70% increased significantly (60/100 vs. 29/100, p = 0.047)." (PMID 26793421, 2016). "In the FGF2 group, FGF2 was locally sprayed onto the surface of ulcers; in the control group, 0.2% (w/v) chlorhexidine solution was sprayed on the ulcers." (PMID 26793421, 2016). "Meanwhile, the average healing time of ulcers was significantly shorter in the FGF2 group than in the control group (Chi square test; p < 0.05)." (PMID 26793421, 2016). "Patients’ diabetic ulcers were randomized into a placebo group (n = 51), a 0.001% (w/v) FGF2 treatment group (n = 49) and a 0.01% (w/v) FGF2 treatment group (n = 50), with the primary outcome being the percentage of patients showing a 75% or greater reduction in the area of ulcer." (PMID 26793421, 2016). "Moreover, an increase in plasma FGF-2 was tied to greater odds of high-grade ulcers." (PMID 37371653, 2023). "Recombinant growth factor proteins, such as FGF2 and PDGF, have been shown to stimulate ulcer-healing processes in clinical applications." (PMID 24675668, 2014). "In one study, FGF-2 was increased in the ulcer edge but not in the wound bed of healing vs. non-healing VLUs." (PMID 35742965, 2022). "Therefore, there is reason to believe that the application of Nal-P-113 advanced the time at which HIOECs primarily produced EGF and FGF-2 and decreased TGF-β1, thus promoting oral ulcer healing." (PMID 30298136, 2018). "FGF2 is produced by mast cells and can help prevent and heal NSAID-related ulcers." (PMID 21858200, 2011). "FGF-2 is one of the most widely studied factors in patients with DFS, and its use as a topically administered drug in non-healing ulcers has been the main topic in recent trials." (PMID 37371653, 2023).